BRCA2 (BRCA2 DNA repair associated)
Diseases named in the same sentence as BRCA2 in open-access papers (continued):
Sharing a sentence is not in itself a finding about the gene and the disease.
cancer (continued). "Among 222 BRCA2 PV carriers, 105 individuals (47.3%) were cancer patients, 109 subjects (49.1%) were healthy and 8 individuals (3.6%) were excluded from the study for lack of sufficient information." (PMID 32380732, 2020). "Since 2018, patients relapsing after previous chemotherapy in the neoadjuvant, adjuvant, or metastatic setting are eligible to treatment with PARP inhibitors such as olaparib and talazoparib, inducing synthetic lethality in BRCA1 or BRCA2 cancers." (PMID 32053991, 2020). "Our results show that in the absence of DNA damage, the number of γH2AX foci or RAD51 foci is comparable in all cell lines including in cells depleted of BRCA2; this is probably due to the high genome instability intrinsic to these cancer cells." (PMID 32286328, 2020). "Large cohorts of breast cancer show that ~ 2% of cancer cases are associated with mutations in BRCA1 and BRCA2 which are also high-risk ovarian cancer susceptibility genes." (PMID 32778766, 2020). "Of the common types of cancer, including pancreatic ductal adenocarcinoma (PDAC) and neuroendocrine tumors (PanNET), ~4 and 1% of PDAC and PanNET possess germline BRCA2 mutations, respectively." (PMID 32269964, 2020). "Cancers in hormonally responsive tissue with low amounts of the BRCA2 protein, would be abnormally stimulated by ovarian hormones." (PMID 32939053, 2020). "As BARD1 variants have also been identified in carriers of known cancer predisposing genes, BRCA1 and BRCA2, it will be important to explore if BARD1 variants modify risk in an epistatic or additive manner in this context." (PMID 32726901, 2020). "The BRCA1 and BRCA2 (BRCA) genes encode key proteins in the homology-directed DNA break repair (HDR) pathway, and their inactivation predisposes individuals to cancer development." (PMID 32444794, 2020). "For the cancer types that performed the worst, liver hepatocellular carcinoma included none of the used oncogenes (AR, KLF4, PDGFRA, and RET) or tumor suppressors (BRCA2, CDKN2A, and TSC1) that were linked to it." (PMID 31900418, 2020). "Lastly, we analyzed BRCA1 and BRCA2 mRNA because of their implications in cancer and DNA repair mechanisms." (PMID 32610620, 2020). "The remaining two studies grouping BRCA1 with BRCA2 compared the patients with cancer in the same institute." (PMID 32349445, 2020). "Multi-gene panels that usually contain known high-risk cancer predisposing genes, such as BRCA1 and BRCA2, were used to determine the prevalence and spectrum of variants in the genes in defined study groups for comparative purposes." (PMID 32726901, 2020). "In EOT biopsies, RAD51 foci deficiency was identified in 77% (17/22) locally assessed TNBC, as well as an ER-positive BRCA2 mutant control cancer." (PMID 32471999, 2020). "Even in the setting of germline BRCA1/BRCA2, which is present in all breast cells, solitary cancers or cancers arising at only several foci occur." (PMID 33196707, 2020). "In this work, we retrospectively collected and analyzed all clinical information of 139 BBC patients who have been genetically tested for germline PVs in different cancer susceptibility genes, including BRCA1 and BRCA2, by NGS-based multi-gene panel testing." (PMID 32854451, 2020). "The panel incorporates genes underlying well-characterized cancer syndromes, such as BRCA1 and BRCA2 (BRCA1/2), along with more recently discovered genes associated with increased cancer risk." (PMID 32090079, 2020).
cancer (continued). "Cell from patient 17 showed clear aberrations, involving several chromosomal regions that encompass cancer-related genes, such as BRCA2 (deletion) and PI3KCA (amplification)." (PMID 32005907, 2020). "All 139 probands were genetically tested for germline PVs in different cancer susceptibility genes, including BRCA1 and BRCA2, by NGS-based multi-gene panel testing." (PMID 32854451, 2020). "When expanding our investigation of other cancer predisposition genes besides ALK and PHOX2B, we detect rare variants such as a nonsense mutation in BARD1 as well as missense variants in CHEK2, BRCA2, and WRN." (PMID 33384420, 2020). "Much of the previous research reporting on psychosocial outcomes after genetic testing for BRCA1 and BRCA2 has enrolled women from academic cancer genetics clinics." (PMID 32393849, 2020). "Both BRCA2 and ATM play important roles in the DNA repair pathways in human and their mutations increase the risk of cancer development." (PMID 32284789, 2020). "Family members of patients with FA who are heterozygous carriers of PV in genes from the fourth module FANCD1 (BRCA2), FANCJ (BRIP1), FANCN (PALB2), FANCO (RAD51C) and FANCS (BRCA1) are at increased risk to develop cancer." (PMID 33371494, 2020). "Lifetime risk, estimated frequency, types (such as ovarian, prostate, pancreatic and others) and characteristics (such as estrogen‐receptor expression) of cancers also vary between individuals with BRCA1 and BRCA2 mutations." (PMID 32638521, 2020). "We further investigated how MMC triggers the apoptosis of BRCA2 monoallelic and biallelic mutant cancer cells." (PMID 32980867, 2020). "The number of recalls and biopsies needed to detect one cancer by biannual MRI were 2.8 and 1.7, respectively, in BRCA1 mutation carriers and 12.0 and 8.0, respectively, in BRCA2 mutation carriers." (PMID 33238387, 2020). "In contrast, FLT3, BRCA1, BRCA2 and PIK3R1 mutations were more frequently detected in patients carrying germline cancer-associated variants." (PMID 30850667, 2019). "Although the DNA damaging agents have shown clinical efficacy in PALB2-, BRCA1- or BRCA2- cancers, tumor cells often develop resistance to these drugs, with tumor recurrence and progression." (PMID 31877165, 2019). "None of the 6-TG analogues tested did affect cell proliferation or apoptosis in wild-type or BRCA2-depleted castration-resistant cancer cells." (PMID 31284411, 2019). "Germline and somatic mutations in genes that promote homology-directed repair, especially BRCA1 and BRCA2, are frequently observed in several cancers, in particular, breast and ovary, but also prostate and other cancers." (PMID 31186630, 2019). "To test the relevance of the identified 11 genes in cellular survival of genomically unstable cancer cells, we modeled genomic instability in vitro by doxycycline-inducible shRNA-mediated depletion of the DNA repair protein BRCA2." (PMID 30177840, 2019). "KHDRBS1 showed a larger difference in expression level when compared to PAXIP1, although differences for both genes were not statistically significant, likely due to the low number of BRCA2 mutant cancers." (PMID 30626869, 2019). "PARPi are currently FDA approved for metastatic breast, ovarian and related cancers, mainly in patients with pathogenic variants in the BRCA1 & BRCA2 genes." (PMID 31159747, 2019). "Other novel, highly scoring gene pair predictions that included cancer associated genes included PARP1 with PBRM1, BRCA2, ARID1A and APC as well as PIK3CA with MAP2K1, ABL1 and EGFR." (PMID 30995217, 2019). "One of these men (1.2%) had more than one cancer (breast and pancreatic) and harbored BRCA2 c.4471_4474delCTGA." (PMID 31892343, 2019). "A number of preceding studies have focused on the role of BRCA2 in mitotic HR as a cancer suppressor; however, meiotic regulation of BRCA2 is less well defined due to the embryonic lethality of Brca2 KO animals." (PMID 30760716, 2019).
cancer (continued). "Similar to what has been described for BRCA2, loss of functional PALB2 is synthetic lethal with poly(ADP-ribose) polymerase (PARP) inhibitors, an innovative class of anti-cancer drugs." (PMID 31586400, 2019). "Our study included two prophylactic mastectomies with BRCA2 cancers, which were diagnosed as DCIS (4 mm and 8 mm in extent, respectively)." (PMID 30820924, 2019). "In this study, we found that forced mitotic entry upon ATR inhibition potentiates cytotoxic effects of PARP inhibition using olaparib in BRCA2‐depleted and Brca2 knockout cancer cell line models." (PMID 31529615, 2019). "It has been demonstrated that protein annexin A1, A2, A4 and A5 play an important role in the occurrence and development of these two cancer types, and BRCA1 and BRCA2 gene mutations are commonly observed in both cancer types." (PMID 31405076, 2019). "Increasing BRCA1 and BRCA2 (collectively termed herein as BRCA) gene testing is required to improve cancer management and prevent BRCA-related cancers." (PMID 31125106, 2019). "Here, specific genes are mutated in particular types of cancer, and patients harboring germline mutations at tumor suppressor genes, such as APC and BRCA1/BRCA2, exclusively develop cancers in specific organs." (PMID 31488818, 2019). "Altogether, our data indicate that BRCA2 inactivation renders cancer cells dependent on the TPX2/Aurora-A signaling axis for their survival." (PMID 30177840, 2019). "The loss of homologous recombination (HR) genes such as BRCA1 and BRCA2 is deleterious to the survival of normal cells, yet it is tolerated in cancer cells." (PMID 30626869, 2019). "Of the acquired mutations (range: 1–7 mutations) in 9 cancer genes, the mutation frequencies of ARID1A (50%) and BRCA2 (50%) were the highest." (PMID 31592412, 2019). "For example, inhibitors of poly(ADP)‐ribose polymerase are effectively used to treat cancers that carry mutations in BRCA1 and/or BRCA2 and have shown promising results in CRC preclinical studies." (PMID 30714316, 2019). "Here the authors identify TNFα signaling as a determinant of viability in BRCA2- inactivated cancer cells." (PMID 30626869, 2019). "The risk and prevalence of specific germline variants in cancer predisposition genes greatly vary across ethnicities and cancer types, as illustrated by the high prevalence of BRCA1 and BRCA2 variants in Ashkenazi Jews." (PMID 31391007, 2019). "High-grade serous ovarian cancer is the cancer subtype for which germline BRCA1/2 mutations are detected at the highest frequency with 8-15% carrying a BRCA1 and 4-8% a BRCA2 mutation." (PMID 31225507, 2019). "Previous studies have shown that RAD52 is required for viability of BRCA1- and BRCA2-deficient cells, suggesting a targeted treatment opportunity via inhibition of RAD52 to specifically kill cancer cells with BRCA deficiency." (PMID 31569559, 2019). "There was a strong significant correlation in BRCA2 carriers between personal cancer history and perceived chance of PC (r = 0.67, p = 0.001, n = 22) and other cancer(s) (r = 0.69, p < 0.001, n = 22)." (PMID 31666883, 2019).
cancer (continued). "Study 42 is a clinical trial, which is used to assess the efficacy of oral Olaparib in patients with advanced cancer and who have a confirmed genetic BRCA1 and/or BRCA2 mutation." (PMID 31577767, 2019). "Taken together, our findings support the importance of genetic changes in BER pathway genes as modifiers of cancer susceptibility for BRCA1 and BRCA2 mutation carriers." (PMID 30747491, 2019). "Cancer cells with deleterious mutations in BRCA1 or BRCA2 have defective HRR and the unrepaired DNA after treatment with PARPi will eventually lead to cancer cell death, a phenomenon called synthetic lethality." (PMID 31404966, 2019). "HR-deficiency is, therefore, a driver of tumorigenesis as demonstrated in cancer cells deficient in BRCA1- and BRCA2 (BRCA) expression or functions." (PMID 31930278, 2019). "Appropriately, BRCA2 carriers had a significantly higher perceived chance of developing other cancer(s) compared to the FPC cohort (mean = 4.18 vs 3.28, p < 0.001)." (PMID 31666883, 2019). "In human cancer cell-lines with defective function of BRCA1, PALB2 or BRCA2, RAD52′s depletion increases damage-associated chromosomal abnormalities, decreases clonal viability, and also reduces the HR activity." (PMID 31652722, 2019). "We argue for the possibility that the ectopic expression of MEILB2, or its fusion protein, in cancer cells can perturb the intrinsic BRCA2 function through direct binding, thus contributing to cancer development by disturbing the mitotic HR pathway." (PMID 30760716, 2019). "In order to minimise the risk of cancer incidence and mortality in women with a BRCA1 or BRCA2 mutation, uptake of both breast MRI and BSO should approach 100%." (PMID 30971774, 2019). "The identification of path_BRCA1 or path_BRCA2 in an affected BC individual enables access to evidence-based screening for family members, and thus facilitates the implementation of appropriate cancer prevention in these families." (PMID 29371908, 2018). "The expression of miR-1245 was much higher, whereas the expression of BRCA2 mRNA was much lower in III + IV grade cancer tissues than in I + II cancer tissues." (PMID 29891014, 2018). "Cancers harboring mutations in “BRCAness” genes, including BRCA1, BRCA2, ATM and PALB2, have been found to be sensitive to DNA crosslinking agents." (PMID 29515757, 2018). "We examined histology-based referral to the Hereditary Cancer Program following an educational prevention campaign recommending BRCA1 and BRCA2 mutation screening for all high-grade serous cancer patients." (PMID 29506471, 2018). "We conducted a population-based retrospective study in the province of British Columbia, Canada that included all patients visiting the Hereditary Cancer Program for genetic counselling for BRCA1 and BRCA2 mutation between 2001 and 2014." (PMID 29506471, 2018). "Underscoring the importance of the coordination of RAD51 activity by BRCA2, BRCA2 mutations in the BRC repeats have been found in cancers." (PMID 30551670, 2018). "The initial report of an association between MLH1 and splicing mutations also associated other cancer related genes such as BRCA1, BRCA2, and NF1 with disrupted splicing." (PMID 29505604, 2018).
cancer (continued). "Here, we genetically ablated PARP1 in a BRCA1- and BRCA2-positive cancer cell line, HCT116, to better understand the role of PARP1 in an otherwise normal, albeit oncogenic, generic background." (PMID 30410680, 2018). "This distribution is similar to that observed in patients with one primary cancer, in whom pathogenic variants in BRCA1 (35.0%), BRCA2 (23.1%), and the mismatch repair genes (15.4%) accounted for almost three-quarters of deleterious mutations." (PMID 30093976, 2018). "Only 5 to 10 % of all types of cancer are basically caused by inborn cancer predisposition such as the so-called familial breast cancer subtype known to be related to the BRCA1 and BRCA2 mutations." (PMID 30092754, 2018). "In summary, this makes saliva a well-suited source for a variety of studies and especially for the detection of cancer biomarkers (e.g., specific germline mutations in BRCA1 and BRCA2) during screening procedures." (PMID 29703267, 2018). "This concept has been harnessed in cancer therapy by the development of PARP inhibitors that selectively inhibit survival of cancer cells carrying mutations in homologous recombination repair genes, such as BRCA1 or BRCA2." (PMID 29983885, 2018). "Serous cancer patients were significantly more likely to be BRCA1 and BRCA2 mutation positive with 21.3% testing positive for either BRCA1 or BRCA2 mutations compared to 7.5% of endometrioid or clear cell patients." (PMID 29506471, 2018). "The lower sensitivity of mammography for BRCA2-related cancers is somewhat more difficult to explain, as histologically these cancers are similar to sporadic cancers." (PMID 30513626, 2018). "Physicians need to be vigilant to the possibility of synchronous or metachronous development of new cancers in the BRCA mutation carriers, especially those with a BRCA2 mutation." (PMID 29433453, 2018). "The Genetic Modifiers of BRCA1 and BRCA2 (GEMO) Group is the French multidisciplinary, collaborative framework for the investigation of genetic factors modifying cancer risk in Hereditary Breast and Ovarian cancer (HBOC) families segregating BRCA1/2 PVs." (PMID 30430080, 2018). "It is also of interest that the human BRCA2 gene neighbors PDS5B, with some cancer-associated mutations likely altering both genes." (PMID 29447171, 2018). "Cancer-associated HR mutations are commonly found in BRCA1 and BRCA2, and can be both germline and somatic." (PMID 30551670, 2018). "Although millions of women, and more recently men, at risk for cancer have been tested for germline genetic variants in BRCA1 and BRCA2, diagnostic sequencing has continued to identify variants with uncertain relevance to cancer risk." (PMID 30586411, 2018). "Our first aim was to evaluate family history of cancer and to detect BRCA1 and BRCA2 mutations in very young Brazilian patients." (PMID 29854292, 2018). "We performed targeted sequencing analyses of all coding exons of BRCA1, BRCA2, and PALB2, as well as sequencing mutational hotspots of 50 cancer-associated genes in the 42 PDAC tumors with paired normal tissues using a next-generation sequencing platform." (PMID 29802286, 2018). "These frequencies are comparable to other published estimates (BRCA2 0.45% in cancer-free Australian women; 0.31% in women of European non-Finnish descent in the Exome Aggregation Consortium, excluding The Cancer Genome Atlas data; Lynch 0.2%)." (PMID 30583724, 2018).